RB1 (RB transcriptional corepressor 1)
Diseases named in the same sentence as RB1 in open-access papers (continued):
Sharing a sentence is not in itself a finding about the gene and the disease.
gastric cancer (38 papers, 1994 to 2025). A primary or metastatic malignant neoplasm involving the stomach. "To further investigate the association between Linc00441and RB1 expression in gastric cancer, we tested the correlation between them using Pearson’s correlation analysis, and identified a strong inverse correlation between Linc00441 and RB1 expression (P < 0.003 and R2 = 0.79)." (PMID 30680063, 2018). "To elucidate the transcriptional regulation of RB1 via KDM5A, we conducted native elongating transcript cap analysis of gene expression (NET-CAGE) to analyze KDM5A-regulated genes in RB1-depleted gastric cancer cells." (PMID 40707487, 2025). "RB1 depletion in AGS gastric cancer cells as well enhanced spherogenesis, exactly as observed in 53KOLS cells." (PMID 40707487, 2025). "Lysine[K]-specific demethylase 5B (KDM5B) was identified as an IL-8 transcription factor in CAFs, and the binding of KDM5B to phosphorylated RB1 limited the transcriptional regulation of IL-8 in gastric cancer cells." (PMID 38862740, 2024). "IHC assays of stomach cancer tissues also showed that RB1 and pRB1 were highly expressed in the tumour cells." (PMID 38862740, 2024). "The prevalence of RB1 (-) in previous studies of gastric cancers using IHC for RB1 is relatively variable, ranging from 0-40% depending on the different criteria used among the studies." (PMID 21447152, 2011). "We report on the analysis of RB1 structure and protein (pRB) expression in gastric carcinomas using Southern blotting, Western blotting and immunohistochemistry." (PMID 7947078, 1994). "Our data therefore suggest that major alterations affecting the RB1 gene are rather infrequent in human gastric carcinomas." (PMID 7947078, 1994). "This pattern was highly reminiscent of that of RB1, indicating that RB1 status might impact PGAM1 status or vice versa in gastric cancers." (PMID 40707487, 2025). "Interestingly, we showed that RB1 was more prone to phosphorylation in gastric cancer cells, and pRB1 was hardly expressed in fibroblasts." (PMID 38862740, 2024). "In this study, we elucidate the impact of lncRNA Linc00441 in linking RB1 and gastric cancer." (PMID 30680063, 2018). "In this study, we found that Linc00441 could recruit DNMT1 to the RB1 promoter and suppressed RB1 expression in gastric cancer cells." (PMID 30680063, 2018). "Linc00441 was found up-regulated and inversely correlated with RB1 expression in gastric cancer." (PMID 30680063, 2018). "We then investigated whether RB1 controls PGAM1 expression through KDM5A in gastric cancer cells." (PMID 40707487, 2025). "The retinoblastoma gene (RB1), a tumor suppressor gene, may have a role in gastric cancer." (PMID 37519424, 2023). "Moreover, targeting of RB1 by this miRNA was also reported in gastric cancer." (PMID 33255928, 2020). "The tumor suppressor-gene retinoblastoma gene (RB1) was decreased in several human cancers including gastric cancer (GC)." (PMID 30680063, 2018). "In addition, miR-215 was able to target RB1 through its 3′-UTR in gastric cancer cells." (PMID 27092489, 2016). "We focused on 587 genes downregulated commonly by RB1 shRNA1 and 2 in the SNU-638 RB1-positive gastric cancer cell line." (PMID 40707487, 2025). "The ratio of mitochondrial gene versus nuclear gene (mitochondrial copy number) changed neither in 53KOSL nor AGS gastric cancer cells following Rb/RB1 depletion." (PMID 40707487, 2025). "Surprisingly, PGAM1 depletion increased sphere formation in gastric cancer cells even without RB1 depletion." (PMID 40707487, 2025). "In contrast, RB1 depletion did not affect histone acetylation in the promoter of PGAM1 of the same gastric cancer cells." (PMID 40707487, 2025). "Indeed, the expression of PGAM1 was downregulated following RB1 depletion in SNU-638 and SNU-601 RB1-positive gastric cancer cell lines however, not in SNU-719 in which RB1 protein has been already inactivated by the product of EBV." (PMID 40707487, 2025).
gastric cancer (continued). "However, comparative studies on the anti-proliferative effects of ginsenoside CK and Rb1 in human gastric cancer cell lines have not been reported." (PMID 36249752, 2022). "For instance, the Retinoblastoma (Rb)-1 tumor suppressor gene is the target of miR-212 in PDAC (increased miR-212 suppresses Rb1 that promotes cell growth), but Rb binding protein-2 (RBP2) is the target in gastric carcinoma and HCC (decreased miR-212 upregulates RBP2 which promotes cell growth)." (PMID 35473623, 2022).
leiomyosarcoma (36 papers, 1989 to 2026). An uncommon, aggressive malignant smooth muscle neoplasm, usually occurring in post-menopausal women. "In 4.2% of pleomorphic liposarcomas and about 10% of leiomyosarcomas, RB1 mutations have been reported." (PMID 37635229, 2023). "Germ line RB1 mutations have been linked to an increased incidence of sporadic leiomyosarcoma, and it is interesting to note that all tumor profiles of leiomyosarcomas in this series identified RB1 mutations." (PMID 26011384, 2015). "Using a probe that detects a polymorphic locus within the RB1 gene we found loss of only one allele (heterozygous deletion) in 33% of soft tissue sarcomas examined, including two leiomyosarcomas, a malignant peripheral nerve sheath tumour, a rhabdomyosarcoma and a chondrosarcoma." (PMID 2765366, 1989). "By integrating large-scale data, we identified two specifically deregulated pathways involved in differentiation/proliferation switch (MYOCD/SRF and E2F1/RB1) in a subgroup of well-differentiated vascular smooth muscle cell-derived cells leiomyosarcomas." (PMID 36672483, 2023). "Immunohistochemistry also demonstrated the loss of RB1 expression in the tumor cells, suggesting that the leiomyosarcoma might have occurred as a secondary cancer on the background of RB." (PMID 37491255, 2023).
leiomyosarcoma (continued). "PORCUPINE highlighted genes and TFs that are enriched in driving heterogeneity among leiomyosarcoma patients, including RB1 and PPP2R1A as target genes, as well as the TFs E2F8 and ZNF282, which could potentially be inhibited." (PMID 37492373, 2023). "Among the detected pathways, we identified pathways that could represent potential targets for treatment of subgroups of leiomyosarcoma patients, including RB1/E2F1 signaling, pathways involved in FGFR signaling, and CTLA4 inhibitory signaling." (PMID 37492373, 2023). "When taken together our results suggest that alterations of the RB1 locus may play an important part in the pathogenesis of soft tissue tumours and particularly in leiomyosarcomas which accounted for four of the eight RB1 alterations observed in this study." (PMID 2765366, 1989).
non-small cell lung carcinoma (36 papers, 1997 to 2025). A group of at least three distinct histological types of lung cancer, including non-small cell squamous cell carcinoma, adenocarcinoma, and large cell carcinoma. "Here we determine the frequency and prognostic significance of RB1 mutation in non small cell lung cancer (NSCLC), restricting inclusion to Stage III and IV patients with linked genomic and clinical data." (PMID 30773851, 2019). "A previous study showed that nicotine increased Rb1 expression in non-small cell lung cancer cell lines, and the knockdown of Rb1 inhibited cell proliferation." (PMID 31635387, 2019). "The enriched “non-small-cell lung cancer” pathway included downregulated RB1 and CDK6, well-known tumor suppressors that regulate cell division and the cell cycle." (PMID 30404194, 2018). "We found that the miR-17 family exerted important effects in the regulation of non-small cell lung cancer, such as in proliferation and cell cycle regulation by targeting the retinoblastoma protein (RB1) and forming a feed forward loop with the E2F1 TF." (PMID 24200043, 2013). "We proposed a model for the miR-17 family, E2F1, and RB1 to demonstrate their potential roles in the occurrence and development of non-small cell lung cancer." (PMID 24200043, 2013). "Deletion of both Rb1/Rbl1, but not Rb1/Rbl2, caused development of non-small cell lung cancers in mice after long latency." (PMID 35368709, 2022). "In addition, miR-661 promoted tumor invasion and metastasis by activating EMT and directly inhibiting RB1 in non-small cell lung cancer." (PMID 32013999, 2020). "Lung tumours and their corresponding tumour-free resection margins from 33 patients who underwent resection of non-small-cell lung cancer (NSCLC) were examined by immunostaining with monoclonal antibodies against cyclin D1 (DCS-6; Novocastra) and pRb (NCL Rb-1; Novocastra)." (PMID 9192978, 1997).
metastatic disease (34 papers, 2003 to 2026). "The detection of the metastatic disease, following the identification of the causal RB1 mutations in tumour-derived DNA or ocular cfDNA, appears to offer the most potential at present." (PMID 33805427, 2021). "Based on single-cell-based sequencing data from the GEMs, we observed that the overexpression of MYCN in combination with the loss of Rb1 resulted in the rapid formation of aggressive, metastatic tumors with neuroendocrine-like features." (PMID 34099734, 2021). "The identification of patients whose disease has metastasised looks more encouraging, as the two highest RB1 mutant allele frequencies observed in the plasma were in patients who went on to develop the metastatic disease." (PMID 33805427, 2021). "The VAFs of RB1 mutations in cfDNA tend to be higher in patients that went on to develop metastatic disease." (PMID 32633890, 2020). "CHMP1A, B2M, and RSU1 loss alterations were significantly enriched in RB1-loss primary tumors at a frequency of 7%–18% above RB1-WT primary tumors and were significantly enriched in RB1-loss metastatic tumors at a frequency of 16%–23% above RB1-loss primary tumors." (PMID 38751776, 2024). "Interestingly, in comparison to recurrently mutated genes identified in the TCGA cohort, we also observed that RB1 mutations were found only in primary and metastatic tumors of LT survivors." (PMID 37400526, 2023). "RB is initiated by the inactivation of the tumor suppressor gene RB1, however, different genomic alterations are involved in the metastatic disease (for review see:)." (PMID 39695086, 2024). "In metastatic tumors, the frequency of homozygous deletions at RB1 was significantly higher among BRCA2d than BRCA2i tumors (17.7% versus 5.2%, padj = 0.0001)." (PMID 35715489, 2022). "Patients with RB1 alterations in the primary tumor had a significantly shorter overall survival (OS) (median OS from metastatic disease 2.32 years; 95% CI: 1.82–3.84; P = 0.006)." (PMID 31874108, 2020). "Cases with matched primary and metastatic tumors harbored identical mutations in both sites (PIK3CA/KRAS and RB1 gene mutations, respectively)." (PMID 26625196, 2016). "Loss of the tumour suppressor genes RB1 (6p21) and CDKN1A (13q14) may explain enrichment of these genetic alterations in our cohort of metastatic tumours." (PMID 35231161, 2022). "RB1 gene alterations were detected in two tumors with secondary endocrine resistance (RB1 R621S in the primary tumor of No. 12 and RB1 loss in the metastatic tumor of No. 15)." (PMID 33854152, 2021).
metastatic disease (continued). "Thus, Taylor and colleagues have shown that three important biochemical pathways, RAS/RAF, PI3K, and RB1, exhibit alterations in 34–43% of primary tumors and 74–100% of metastatic tumors." (PMID 31366128, 2019). "However, the expression of RB1 was significantly higher in non-metastatic diseases group." (PMID 35420053, 2022). "The high frequency of mutations in the genes RB1, TSC1 and FOXA1 in the metastatic samples with few or no concordant cases also suggests these genes are similarly relevant to the biology of metastatic disease." (PMID 32811538, 2020).